RN7SL813P (RNA, 7SL, cytoplasmic 813, pseudogene)
Gene: Miscellaneous RNA gene on chromosome 2 (168,451,324 to 168,451,606, forward strand). Ensembl gene ENSG00000241074.
Homologues: Orthologues: chimpanzee Metazoa_SRP (100% identical), macaque Metazoa_SRP (96% identical). Paralogues in human: RN7SL1 (83% identical), RN7SL2 (83% identical), RN7SL597P (83% identical), RN7SL448P (82% identical), RN7SL3 (82% identical), RN7SL606P (82% identical), RN7SL493P (81% identical), RN7SL709P (81% identical), RN7SL45P (81% identical), RN7SL126P (81% identical), RN7SL655P (81% identical), RN7SL665P (81% identical), and 706 more.